TIMP2 (TIMP metallopeptidase inhibitor 2)
Diseases named in the same sentence as TIMP2 in open-access papers (continued):
Sharing a sentence is not in itself a finding about the gene and the disease.
cervical carcinoma (continued). "The aim of this study was to determine plasma levels of M-CSF, MMP-2 and TIMP-2 in comparison to CA 125 and SCC-Ag concentrations in patients with cervical cancer in relation to the control group (healthy subjects)." (PMID 30820752, 2020). "In vitro, T2PEX+TM and T2PEX suppress the gelatinolytic and invasive abilities of cervical carcinoma (HeLa) and HT1080 fibrosarcoma cancer cells significantly better than wild type TIMP-2." (PMID 28186971, 2017). "After treating with IL-17A, the expression of MMP2 and MMP9 proteins in cervical cancer cell lines (C33A and Caski) was increased, meanwhile the expression of TIMP-1 and TIMP-2 proteins was decreased." (PMID 25250801, 2014). "On the other hand, using a series of 150 cervical carcinomas and 152 CIN lesions Branca and co-workers observed that TIMP-2 is down-regulated in invasive tumors and correlated low levels of the inhibitor with poor prognosis and higher invasive potential." (PMID 22438955, 2012). "Furthermore, miR-20a expression has been related to the malignant process of cervical cancer, especially invasion and metastasis by targeting ATG7 and TIMP2." (PMID 27916938, 2016). "Our results suggest that miR-20a expression may be related with malignant process of cervical cancer, especially invasion and metastasis by targeting ATG7 and TIMP2." (PMID 25803820, 2015). "IL-17A could promote the migration and invasion of cervical cancer cell via up-regulating MMP2 and MMP9 expression, and down-regulating TIMP-1 and TIMP-2 expression via p38/NF-κB signal pathway." (PMID 25250801, 2014). "Previous studies have also shown that the expression of MT1-MMP, MMP-2 and TIMP-2 correlated well in most, if not all, cervical cancer cell lines." (PMID 23967226, 2013).
glioma (28 papers, 2003 to 2024). A benign or malignant brain and spinal cord tumor that arises from glial cells (astrocytes, oligodendrocytes, ependymal cells). "Visual inspection of the funnel plot revealed asymmetry in analysis of the association between MMP-2 or TIMP-2 expression and glioma grade, indicating the possibility of publication bias." (PMID 26729052, 2017). "Lastly, there was only one study that reported the data about MMP-2 expression and the OS and only two studies analyzed the association between MMP-2/TIMP-2 and the grade of gliomas." (PMID 26729052, 2017). "On the other hand, DHMEQ treatment was able to reduce in dose-dependent manner the expression of the metastasis-promoting genes MMP-2, MMP-14, TIMP-2, and uPA, all of which have been implicated in the regulation of invasion in glioma cells." (PMID 23533755, 2013). "Immunohistochemical staining also demonstrated that MMP9 and SPHK1 levels were apparently reduced, but LASS2 and TIMP2 levels were increased in glioma xenografts derived from U-87 MG-pLV-LASS2 cells compared with those derived from U-87 MG-pLV cells." (PMID 35517425, 2022). "S. typhimurium ΔppGpp that expressed tissue inhibitor of metalloproteinases 2 (TIMP-2) reduced the size of glioma brain tumours in BALB/c mice and increased survival by 60%." (PMID 36144335, 2022). "TIMP2 was positively correlated with metastasis in multiple cancers, including high-grade glioma (R = 0.289, P < 0.001), non-small-cell lung cancer (R = 0.393, P < 0.001), and BCa (R = 0.403, P < 0.001)." (PMID 36304987, 2022). "TIMP2 is involved in glioma inhibition by different drugs as an intermediate link in the upregulated expression in different studies." (PMID 34781885, 2021). "In glioma cells, TIMP2 was negatively regulated by miR-221/222 and this was proposed to favor invasiveness." (PMID 30833639, 2019). "miR-20a is greatly upregulated in glioma stem cells and potently enhances glioma stem cell invasion through directly targeting TIMP-2." (PMID 29861871, 2018). "TIMP2 overexpression suppressed glioma angiogenesis and metastasis, which was enhanced by miRNA-221/222." (PMID 29383201, 2017). "TIMP2 was also reported to significantly inhibit invasion ability in glioma by negatively regulating miR-20a." (PMID 29220395, 2017). "Due to the limited number of studies included, the findings about the impact of MMP-2 expression or MMP-2/TIMP-2 on the prognosis of gliomas should be interpreted with caution." (PMID 26729052, 2017). "In order to evaluate the essential roles and clinical utilities of MMP-2 and TIMP-2 in gliomas, we performed a meta-analysis." (PMID 26729052, 2017). "Many studies have shown that MMP-2 and TIMP-2 play crucial roles in various human cancers, including gliomas." (PMID 26729052, 2017). "So far, the prognostic value of matrix metalloproteinase 2 (MMP-2) and tissue inhibitor of matrix metalloproteinase 2 (TIMP-2) expressions in patients with gliomas has been widely reported, especially in China." (PMID 26729052, 2017). "An imbalance between MMP-2 and TIMP-2 has an important role in glioma invasion by degradation of the ECM." (PMID 26245666, 2015). "In addition, TGF-β2 induced the expression of matrix metalloprotease-2 (MMP2) and suppressed the expression of tissue inhibitors of metalloproteinases (TIMP)-2, which degraded the extracellular matrix to promote glioma invasion." (PMID 35600367, 2022). "In addition, the levels of the tissue inhibitors of metalloproteinases (TIMP)-1 and TIMP-2 decreased after FABP6 reduction in glioma cells." (PMID 34685761, 2021). "Interestingly, expression of TIMP2, an inhibitor of TβRIII shedding, is reduced in human glioma cell lines exposed to TGF-β2." (PMID 33772427, 2021).
glioma (continued). "Firstly, the heterogeneity among studies about TIMP-2 expression and glioma grade may affect the results of the present meta-analysis." (PMID 26729052, 2017). "Finally, 25 studies were included in the meta-analysis, of which 24 studies were related to MMP-2 and gliomas and seven studies for TIMP-2 and gliomas." (PMID 26729052, 2017). "In addition, TGFβ2 induces the expression of MMP2 in glioma cells and suppresses the expression of tissue inhibitor of metalloproteinases (TIMP)-2, which degrades the extracellular matrix and subsequently promotes glioma invasion." (PMID 29410971, 2017). "Some studies reported that high TIMP-2 expression was associated with high-grade gliomas, but some studies gave the contrary results, and others even showed that TIMP-2 expression was not correlated with the WHO grade of gliomas." (PMID 26729052, 2017). "Two studies reported the association between MMP-2/TIMP-2 and the WHO grade of gliomas." (PMID 26729052, 2017). "MMP-2 and TIMP-2 expressions in the tissues of gliomas were only investigated by IHC method." (PMID 26729052, 2017). "MMP-2/TIMP-2 testing may predict the WHO grade of gliomas, and MMP-2 expression may serve as a biomarker for the prognosis of patients with gliomas, which required to be further certified by future studies." (PMID 26729052, 2017). "Thus, we conducted a meta-analysis to determine the correlation of MMP-2 and TIMP-2 expressions with the prognosis of patients with gliomas." (PMID 26729052, 2017). "Furthermore, many proteins associated with tissue remodelling and cellular invasion (e.g. TIMP1, TIMP2) were clearly deregulated in the dataset in a manner suggesting a heightened state of cellular plasticity (e.g. ‘glioma invasiveness signalling’)." (PMID 25800737, 2015). "Glioma M2-polarized macrophages induce glioma cell migration by the release of anti-inflammatory cytokines like TGF-β, the upregulation of MMP-2 and the suppression of TIMP-2." (PMID 38969910, 2024). "In C6 rat glioma cells, it was shown that JNK activity controlled the expression of both MT1-MMP and TIMP-2, which led to the activation of MMP-2 in these cells." (PMID 38984107, 2024). "Studies have shown that TGF- β can promote the metastasis of glioma by upregulating synthesis and matrix metalloproteinase-2 (MMP-2), and downregulating metalloproteinase-2 (TIMP-2)." (PMID 36506566, 2022). "And some researchers found that the mechanism of MMP14 in glioma mainly works by cutting CD44, or via the combination of TIMP-2 and MMP14 to activate MMP-2 and MMP9 to enhance tumor invasion and tumor cell proliferation." (PMID 34712139, 2021). "The volume of glioma model cultured by C6 cell line in rats can be significantly reduced, treated by MMP-2 specific inhibitor factor (TIMP-2), and accompanied with the degeneration and necrosis of blood vessel." (PMID 26788112, 2015). "Similar to TIMP2, the RHOA gene was also down-regulated in cisplatin-treated glioma cells, and the decreased expression levels were also confirmed through real time PCR analysis." (PMID 21637621, 2010). "Examination of MMP-2, MT1-MMP, a membrane-bound MMP which is thought to facilitate rapid processing of pro-MMP-2, and TIMP-2 showed that the expression patterns of MMP-2 and MT1-MMP were very similar among the examined glioma cell lines." (PMID 14647148, 2003). "Western blot analysis demonstrated that the protein levels of LASS2 and TIMP2 were apparently elevated, accompanied by reductions in SPHK1, MMP2, and MMP9 protein levels, in glioma xenografts derived from U-87 MG-pLV-LASS2 cells compared with those derived from U-87 MG-pLV cells." (PMID 35517425, 2022). "Therefore, adenoviral delivery of TIMP2 and PTEN/MMAC1 cDNA to human glioma cells significantly inhibited invasive phenotype and growth of gliomas in vivo." (PMID 33790740, 2021).
glioma (continued). "The results revealed support for significant publication bias in MMP-2 group (t = 3.90, P = 0.001) while did not reveal any publication bias among studies on TIMP-2 expression and glioma grade (t = −0.69, P = 0.521)." (PMID 26729052, 2017). "There were seven studies involving 463 patients on TIMP-2 expression and the WHO grade of gliomas." (PMID 26729052, 2017). "And, MMP-2/TIMP-2 rose with the increase of glioma grade, which may be used as criteria of WHO grade in gliomas." (PMID 26729052, 2017). "Interestingly, it was previously reported in gliomas that JNK may function as a positive regulator of MMP2 activity, not by interfering with the MMP expression but by the regulation of TIMP2 expression, an activator of the pro-MMP2." (PMID 25596741, 2015). "However, TIMP2 was not significantly correlated with any of the 14 functional states in glioma." (PMID 36304987, 2022).
colorectal cancer (24 papers, 1997 to 2025). A primary or metastatic malignant neoplasm that affects the colon or rectum. "Tissue inhibitor of metalloproteinases 2 (TIMP‐2) has been shown to be associated with colorectal cancer (CRC), but its correlation with 5‐Fu resistance in colorectal cancer has not been thoroughly studied." (PMID 40118773, 2025). "Further, the less common TIMP2-418C allele showed an overall significant association with colorectal cancer (P=0.029)." (PMID 30988064, 2019). "Further, the less common TIMP2-418C allele also showed a significant association with an increased risk of colorectal cancer." (PMID 30988064, 2019). "In the present study, we found that the heterozygous genotype (GC) of TIMP2-418G/C SNP was significantly associated with an increased risk of colorectal cancer." (PMID 30988064, 2019). "In other words, the females carrying the variant allele, TIMP2-418C in heterozygous form (GC) or variant homozygous form (CC) were at an increased risk of developing colorectal cancer in comparison with males." (PMID 30988064, 2019). "The TIMP2-418C allele was associated with an increased risk of the colorectal cancer [OR, 1.74 (95%CI, 1.05–2.88); P=0.029]." (PMID 30988064, 2019). "The TIMP2-418G/C SNP has been previously reported to be associated with risk modulation in colorectal cancer and other cancers including breast cancer, gastric cancer; oral cancer, prostate cancer, ovarian cancer, head and neck cancer, and non-Hodgkin’s lymphoma." (PMID 30988064, 2019). "We established an autocrine mechanism through which elevated TIMP-2 protein levels sustained colorectal cancer cell resistance to 5-Fu by constitutively activating the ERK/MAPK signaling pathway." (PMID 35022331, 2022). "Their data suggest that MMPs, as well as their inhibitors TIMP-1 and TIMP-2, play a crucial role in colorectal cancer." (PMID 36250005, 2022). "Using a cytokine array, we established that tissue inhibitor metalloproteinase 2 (TIMP-2) is highly expressed in 5-Fu resistant colorectal cancer patients." (PMID 35022331, 2022). "In conclusion, a novel TIMP-2-ERK/MAPK mediated 5-Fu resistance mechanism is involved in colorectal cancer." (PMID 35022331, 2022). "High levels of TIMP2 synthesis predict better survival in both endometrial cancer and pancreatic cancer, and TIMP2 reportedly regulates colorectal cancer metastasis." (PMID 36291151, 2022). "Accordingly, the reduced expression of the MMP2 inhibitor TIMP2 correlates with colorectal cancer invasion and a worse prognosis." (PMID 34201494, 2021). "Previous studies have demonstrated that miR-552 functions as a potential oncogene in a series of cancer types and figure out several downstream targets, such as AJAP1 in liver cancer, Smad2 and DACH1 in colorectal cancer, TIMP2 and WIF1 in osteosarcoma 28-32." (PMID 33867818, 2021). "In the present study, we systematically evaluated the possible association between TIMP2-418G/C and TIMP3-1296T/C SNPs and susceptibility to colorectal cancer in Kashmiri population through a case–control setup." (PMID 30988064, 2019). "The overall association between the TIMP2-418G/CSNP and the modulation of colorectal cancer risk was found to be significant (P=0.019)." (PMID 30988064, 2019). "The reduced TIMP2 expression which translates into increased MMP2/TIMP2 ratio has been reported in colorectal cancer." (PMID 30988064, 2019). "In the present study, we evaluated the methylation of the CDH1, DAPK, CDKN2A, and TIMP2 genes in five colorectal cancer patients from Manaus, the capital of the Amazon state in Brazil." (PMID 26363785, 2015). "In conclusion, the aim of the present study was to assess the serum levels of MMP-2 and TIMP-2 as well as tumor tissue expression of these proteins in patients with colorectal cancer." (PMID 24395652, 2014).
colorectal cancer (continued). "The serum levels of MMP-2 correlated significantly with serum levels of TIMP-2 in colorectal cancer patients (p < 0.001) and intensity of this protein expression in inflammatory (p = 0.012) and normal colorectal cells (p = 0.039)." (PMID 24395652, 2014). "The objective of the study was the assessment of serum levels and tissue expression of matrix metalloproteinase 2 (MMP-2) and tissue inhibitor of matrix metalloproteinases 2 (TIMP-2) in patients with colorectal cancer (CRC)." (PMID 24395652, 2014). "Therefore, up-regulation, down-regulation and rescue experiments proved that an autocrine mechanism is involved in TIMP-2 induced colorectal cancer cell resistance to 5-Fu." (PMID 35022331, 2022). "The reduced TIMP2 expression has been reported in colorectal cancer." (PMID 30988064, 2019). "The expression profile of TIMP2 has been studied in colorectal cancer." (PMID 30988064, 2019). "In the present study, we investigated the role of functional TIMP2-418G/C and TIMP3-1296T/CSNPs in the promoter region of TIMP2 and TIMP3 genes, respectively, as a potential colorectal cancer risk factor in a case–control study design with 142 case subjects and 184 control subjects." (PMID 30988064, 2019). "Moreover, the immunoreactivity of MMP-2 and TIMP-2 in colorectal cancer tissue correlated with the expression of these proteins in the interstitial inflammatory infiltrate cells as well as with the serum levels of TIMP-2 in CRC patients." (PMID 24395652, 2014). "Therefore, targeting TIMP-2 or ERK/MAPK may provide a new strategy to overcome 5-Fu resistance in colorectal cancer chemotherapy." (PMID 35022331, 2022). "Our findings suggest that MMP-2 and TIMP-2 might play a role in the process of colorectal cancer invasion and metastasis, but the significance of their interactions with tumor stroma and interstitial inflammatory infiltration in colorectal neoplasia require further elucidation." (PMID 24395652, 2014). "We investigated whether the expression of membrane-type-1 matrix metalloproteinase (MT1-MMP), matrix metalloproteinase-2 (MMP-2) and tissue inhibitor of metalloproteinase-2 (TIMP-2) was consistent with the proposed roles of these proteins in promoting metastasis in colorectal cancer." (PMID 10901373, 2000). "Multiple SASP-linked proteins that rose in GCR-exposed mouse serum including, PSAP, THBS1, TIMP2, CST3, and PSMA6 are broadly detected in human malignancies, including breast and colorectal cancers were upregulated after GCR exposure." (PMID 41516087, 2025). "In colorectal cancer patients, higher MMP:TIMP-2 ratio or reduced TIMP-2 expression in serum or tissue is known to be directly correlated with increased colorectal tumour invasion and poor prognosis." (PMID 35953652, 2023). "Based on their relevance in colorectal cancer invasion, we also evaluated the mRNA expression of the matrix metalloproteinase 2 (MMP2) and its inhibitor TIMP2." (PMID 34201494, 2021). "Here, we analyzed the methylation pattern from five colorectal cancer patients from the Amazon state in Brazil for four tumor suppressor genes, viz.: DAPK, CDH1, CDKN2A, and TIMP2 by employing a polymerase chain reaction (PCR) specific to methylation." (PMID 26363785, 2015). "However, little is known about the comparison of the levels of MMP-2 and TIMP-2 in the sera of CRC patients with an expression of MMP-2 and its inhibitor in colorectal cancer tissue." (PMID 24395652, 2014). "We did not confirm any significant correlation between MMP-2 and TIMP-2 expression in colorectal cancer cells or normal cells and tumor stage, tumor size (T), nodal involvement (N), presence of distant metastases (M), or resectability of tumor." (PMID 24395652, 2014). "Immunohistochemical detection of MT1-MMP and TIMP-2 might be useful for monitoring infiltration in colorectal carcinoma but is not correlated with distant metastases." (PMID 10901373, 2000).
colorectal cancer (continued). "However, according to the best of our knowledge, there is no study comparing serum levels of MMP-2 and TIMP-2 in colorectal cancer patients with their expression in colorectal tumor tissue: cancer cells, inflammatory infiltrate cells, and colorectal cells from adjacent normal tissue." (PMID 24395652, 2014). "Other proteins, including TIMP-2, IGF-1, and HIF-1α, demonstrate increased expression in clones of peritoneal metastasis from colorectal cancer as opposed to primary colorectal tumors or liver metastases originating from colorectal cancer." (PMID 37689664, 2023).